ENPP2 (ectonucleotide pyrophosphatase/phosphodiesterase 2)
Description:
Secreted lysophospholipase D that hydrolyzes lysophospholipids to produce the signaling molecule lysophosphatidic acid (LPA) in extracellular fluids. Its major substrate is lysophosphatidylcholine. Can also act on sphingosylphosphorylcholine producing sphingosine-1-phosphate, a modulator of cell motility. Can hydrolyze, in vitro, bis-pNPP, to some extent pNP-TMP, and barely ATP. Involved in several motility-related processes such as angiogenesis and neurite outgrowth. Acts as an angiogenic factor by stimulating migration of smooth muscle cells and microtubule formation. Stimulates migration of melanoma cells, probably via a pertussis toxin-sensitive G protein. May have a role in induction of parturition. Possible involvement in cell proliferation and adipose tissue development (Probable). Required for LPA production in activated platelets, cleaves the sn-1 lysophospholipids to generate sn-1 lysophosphatidic acids containing predominantly 18:2 and 20:4 fatty acids. Shows a preference for the sn-1 to the sn-2 isomer of 1-O-alkyl-sn-glycero-3-phosphocholine (lyso-PAF).
Synonyms: LysoPLD; ATX; PDNP2; PD-IALPHA; ATX-X; AUTOTAXIN; NPP2
Tractability: Small molecule: a drug acting on it is in phase 2 or 3 trials; a structure with a bound ligand is known; a high-quality ligand is known; it belongs to a druggable protein family. Antibody: UniProt places it where antibodies can reach, with high confidence; its Gene Ontology location is reachable by antibodies, with high confidence; UniProt predicts a signal peptide or a membrane-spanning region. PROTAC: a small molecule that binds it is known.
Target class: Enzyme
Chemical probes: BI-2545 (high quality), Ziritaxestat (high quality)
Gene: Protein-coding gene on chromosome 8 (119,557,085 to 119,673,453, reverse strand). Ensembl gene ENSG00000136960.
Subcellular location: Secreted
Subcellular location (Human Protein Atlas): Golgi apparatus; Nucleoplasm; Actin filaments; Predicted to be secreted
Pathways (Reactome):
Metabolism: Vitamin B5 (pantothenate) metabolism
Gene Ontology:
Molecular function: alkylglycerophosphoethanolamine phosphodiesterase activity; calcium ion binding; phosphatidylcholine lysophospholipase activity; phospholipase D activity; zinc ion binding; hydrolase activity; phosphodiesterase I activity; metal ion binding; nucleic acid binding; polysaccharide binding; scavenger receptor activity
Biological process: phosphatidylcholine catabolic process; phospholipid catabolic process; positive regulation of epithelial cell migration; positive regulation of lamellipodium morphogenesis; regulation of cell migration; sphingolipid catabolic process; immune response; vesicle-mediated transport
Cellular component: extracellular region; plasma membrane
Genetic constraint (gnomAD): Loss-of-function variants: 22 observed, 49.2 expected, observed/expected ratio (o/e) 0.45, 90% interval 0.32 to 0.64. The upper end of that interval is the gene's LOEUF score, 0.64, which puts it in group 2 of 6, group 1 being the genes least tolerant of losing a copy. Missense variants: 438 observed, 544.61 expected, observed/expected ratio (o/e) 0.8, 90% interval 0.74 to 0.87. Synonymous variants: 182 observed, 187.79 expected, observed/expected ratio (o/e) 0.97, 90% interval 0.86 to 1.1.
Homologues: Orthologues: chimpanzee ENPP2 (99% identical), macaque ENPP2 (98% identical), pig ENPP2 (96% identical), dog ENPP2 (95% identical), rabbit ENPP2 (95% identical), mouse Enpp2 (94% identical), rat Enpp2 (94% identical), guinea pig ENPP2 (82% identical), tropical clawed frog enpp2 (75% identical), zebrafish enpp2 (66% identical), Caenorhabditis elegans C27A7.3 (21% identical), Caenorhabditis elegans enpp-1 (21% identical), and 1 more. Paralogues in human: ENPP1 (44% identical), ENPP3 (43% identical), ENPP4 (17% identical), ENPP5 (14% identical), ENPP7 (14% identical), ENPP6 (13% identical).
Diseases named in the same sentence as ENPP2 in open-access papers:
ENPP2 is named in the same sentence as 102 diseases in open-access papers, as found by Europe PMC text mining. Sharing a sentence is not in itself a finding about the gene and the disease. The quoted sentences say what the papers report.
breast carcinoma (20 papers, 2010 to 2025). "Furthermore, increased Enpp2 expression is associated with many types of cancers, such as melanoma, breast cancer, glioblastoma, lung adenocarcinoma, and ovarian cancer." (PMID 37795611, 2023). "Similarly, in breast cancer cell lines, a promoter-associated CpG (cg02156680) of ENPP2 was found highly methylated." (PMID 34769391, 2021). "ENPP2 is involved in the clinical progression of breast carcinoma, and CALR exerts pro-tumor activities that are consistent with its effects on gene expression, cell proliferation, and immune response." (PMID 39201614, 2024). "We explored various databases to correlate the expression patterns of TNF-α, NF-κB signaling and ATX (ENPP2) expression in breast cancers." (PMID 38201482, 2023). "The Timer database, which is used for analyzing the correlation between genes in tumors, showed a positive correlation between TNF-α and ENPP2 expression in different subtypes of breast cancer." (PMID 38201482, 2023). "We also analyzed the bc-GenExMinor database for the expression of ENPP2 in different subtypes of breast cancer patients." (PMID 38201482, 2023). "The current review aims to gather the latest findings about aberrant signaling through ATX-LPA in breast cancer and discusses the role of ENPP2 expression and epigenetic modification, giving insights with translational value." (PMID 36358855, 2022). "The results shown that the expression of TRRERF1, PER1, TUFT1, CCND1, and ENPP2 genes was significantly different in breast cancer and adjacent tissues (p < 0.0001)." (PMID 33365308, 2020). "Elevated ENPP2 expression has been previously reported in several carcinomas, such as liver cancer, and studies about ENPP2 in breast cancer are all cell-based." (PMID 32412047, 2020). "The expression of ENPP2 is increased in different tumors including hepatocellular carcinoma, melanoma, ovarian and breast cancers." (PMID 31251802, 2019). "To determine which receptor may be activated, we assessed the expression of the three LPA receptors overexpressed in the murine breast cancer model and Enpp2 (ATX) at the gene expression and protein levels." (PMID 27808166, 2016). "The results for seven candidate genes—CCDC181, GCM2, ITPRIPL1, ENPP2, LOC643719, ZNF177 and ADCY4—were successfully validated by sequencing and stable detection in ccfDNA from the plasma of Taiwanese patients with breast cancer." (PMID 33803633, 2021). "Aberrant methylation patterns of the CCDC181, GCM2, ITPRIPL1, ENPP2, LOC643719, ZNF177 and ADCY4 genes were identified and further evaluated in paired tumor and normal tissues of breast cancer patients." (PMID 33803633, 2021). "The methylation patterns of the CCDC181, GCM2, ITPRIPL1, ENPP2, LOC643719, ZNF177 and ADCY4 genes were further determined in plasma samples from healthy and early breast cancer patients." (PMID 33803633, 2021). "Aberrant methylation of CCDC181, GCM2, ITPRIPL1, ENPP2, LOC643719, ZNF177 and ADCY4 was found in breast cancer patients from the Taiwanese and TCGA cohorts using the methylation array." (PMID 33803633, 2021). "Autotaxin (ATX), also known as phosphodiesterase-I alpha (PD-I alpha) or ecto-nucleotide pyrophosphatase/phosphodiesterase 2 (NPP2 or ENPP2), is overexpressed in various tumors, including gastric cancer, ovarian cancer, breast cancer." (PMID 21406114, 2011). "To further determine the methylation pattern of breast cancer tissues in the Taiwanese cohort, we analyzed the methylation levels of CCDC181, GCM2, ITPRIPL1, ENPP2, LOC643719, ZNF177 and ADCY4 in tumors and adjacent normal tissue in Taiwanese breast cancer patients." (PMID 33803633, 2021). "However, poorer sensitivity or specificity in plasma for the early detection of breast cancer was found for the LOC643719, ENPP2, ADCY4 and RASSF1 genes." (PMID 33803633, 2021).
breast carcinoma (continued). "This indicated that the expression of ENPP2 in primary tumors of breast cancer patients was independent of the tumor size, grade, node, estrogen receptor (ER) and progesterone receptor (PgR) status." (PMID 20305819, 2010).
melanoma (17 papers, 2012 to 2026). A malignant, usually aggressive tumor composed of atypical, neoplastic melanocytes. "First identified in melanoma cell culture studies, autotaxin (ATX) is a crucial enzyme encoded by the ectonucleotide pyrophosphatase/phosphodiesterase family member 2 (ENPP2) gene." (PMID 41499228, 2026). "We found melanoma tumors with high ENPP2 expression were enriched for an “exhausted” CD8 T cell profile by transcriptomic gene analysis." (PMID 37270644, 2023). "It has been reported that the expression of either LPCAT1 or ENPP2 is increased and some LPCs are decreased in diverse human tumors including hepatoma, melanoma, and acute myeloid leukemia." (PMID 34869922, 2021). "In addition to miR-214/CADM1 and miR-182/RECK, recent studies have demonstrated that the exosomal miR-29c-3p derived from M1 macrophages inhibits the invasiveness of melanoma cells through ectonucleotide pyrophosphatase/phosphodiesterase 2 (ENPP2)." (PMID 40861221, 2025). "ATX, which is encoded by the ENPP2 gene, is responsible for the generation of LPA from LPC and has been shown to be overexpressed in a number of tumour types, such as melanoma and cancers of the thyroid, breast, pancreas and stomach, leading to increased levels of LPA in tumours." (PMID 33240646, 2020). "On the other hand, reduced ENPP2 expression is observed after decreased expression of the NFAT1, resulting in a reduction of growth and metastasis of melanoma cells." (PMID 36358855, 2022). "A different pattern was described in HCC, melanoma, CRC, LC and PC, showing a malignant-specific profile of ENPP2 methylation." (PMID 34769391, 2021). "Most importantly, all six DMCs of ENPP2 located at TSS in the promoter or at the 1st exon showed increased methylation across different cancer types, including HCC, melanoma, CRC, LC and PC." (PMID 34769391, 2021). "In silico analysis of ENPP2 conducted in different cancer types such as Pancreatic cancer (PC), LC, Colorectal cancer (CC), melanoma and HCC revealed a specific methylation pattern, as ENPP2 was hypermethylated in promoter and hypomethylated in gene body, accordingly." (PMID 36358855, 2022). "SDC4 mRNA is expressed at high levels in almost all primary tumor entities, as opposed to ENPP2 mRNA whom highest levels could be found in renal cancers and melanoma, two cancer types that were not addressed in our study." (PMID 30237860, 2018).
hepatocellular carcinoma (11 papers, 2018 to 2026). A malignant tumor that arises from hepatocytes. "In order to illuminate the correlation between HBV infection and ENPP2 expression, plasmid pSM2-HBV was transfected into hepatoma cells, then ENPP2 expression and secretion was tested." (PMID 34805271, 2021). "Of note, ENPP2 expression has recently been considered to be very important in hepatoma development, including replication of hepatitis B virus and hepatitis C virus." (PMID 34869922, 2021). "Consistent with clinical data, ENPP2 expression and secretion were significant higher in hepatoma cells, including Huh7 and HepG2, compared within normal hepatocytes both in RNA and protein level." (PMID 34805271, 2021). "ENPP2, an enzyme that acts on lyso-PLs to produce lysophosphatidic acid, plays a very important role in hepatoma development, including the growth of hepatitis B virus and hepatitis C virus, and high-grade hepatomas are reported to have high ENPP2 expression." (PMID 37247782, 2023). "In addition, aHSCs strengthened hepatoma cell proliferation, migration in vitro, and promoted tumorigenesis synergistically with HBV in vivo; a loss-function assay further verified that ENPP2 is essential for HBV/aHSC-induced HCC progression." (PMID 34805271, 2021). "In our results, we confirmed that HBV enhanced the secretion of ENPP2 in hepatoma cells, and ENPP2 is reported to have the function to activate HSC, these points imply that HBV may activate HSC via ENPP2." (PMID 34805271, 2021). "Therefore, ENPP2 is expected to be a promising target for hepatoma suppression, and the possibility of reducing ENPP2 activity by GGA will pave the way for future hepatoma prevention." (PMID 34869922, 2021). "In vitro, HBV upregulated ENPP2 expression and secretion in hepatoma cells and promoted hepatoma cell proliferation, colony formation, and migration via enhancement of ENPP2; downregulation of ENPP2 expression or inhibition of its function suppressed HCC progression." (PMID 34805271, 2021). "HBV also promoted hepatoma cell migration, while knocking down of ENPP2 could inhibit hepatoma cell migration even though cells were transfected with pSM2-HBV." (PMID 34805271, 2021). "Moreover, high ENPP2 expression in hepatoma is detected in patients with histological grade II/III." (PMID 34869922, 2021). "Besides, our results indicated that knocking down of ENPP2 expression or inhibiting ENPP2 function could impede hepatoma cell proliferation, migration, and xenograft tumor formation induced by HBV." (PMID 34805271, 2021). "In the liver, genetic deletion of Enpp2 from hepatocytes attenuated hepatocellular carcinoma (HCC) development, revealing ATX/LPA autocrine effects in hepatocyte metabolism." (PMID 29951481, 2018). "The CCK-8 assay displayed that compared to those transfected with control vector, hepatoma cells transfected with pSM2-HBV had a stronger ability of proliferation, while knocking down of ENPP2 could inhibit cell proliferation significantly." (PMID 34805271, 2021). "In order to evaluate ENPP2 gene expression levels in patients with cholangiocarcinoma (CCA), hepatocellular carcinoma (HCC), colorectal cancer (CRC), and pancreatic cancer (PC), we used data from TCGA database comparing them with peritumoral counterpart and GTEx database." (PMID 37550785, 2023).
Obesity (11 papers, 2010 to 2025). Accumulation of substantial excess body fat. "Adipocyte ENPP2 expression was accompanied by a substantial increase in adipogenesis in individuals exhibiting type II diabetes associated with obesity." (PMID 39731014, 2024). "We found that several serum leptin-associated genes including Peli3, Creb1, and Enpp2 and serum insulin-associated genes such as Centg1 are associated with obesity and colonic diseases." (PMID 28170448, 2017). "Moreover, dbp (D site albumin promoter binding protein) has been previously related to diabetes in liver and heart, while Enpp2 (autoxin) is associated to severe type 2 diabetes and linked to obesity-associated pathologies in adipose tissues." (PMID 20487547, 2010). "In recent years, it has been shown that ENPP2 is closely correlated with obesity and disorders of glucolipid metabolism in obese individuals." (PMID 39731014, 2024). "The authors also showed that partial genetic reduction of ENPP2 levels ameliorated obesity and systemic insulin resistance in a high-fat diet mouse model." (PMID 36910157, 2023). "A possible LPAR through which LPA mediates this effect is LPAR1 since the Lpar1-knock out KO is also resistant to diet-induced obesity as is the Enpp2-KO." (PMID 31652837, 2019). "Increases in ATX levels in db/db mice correlate with obesity, and plasma levels of ATX are reduced by adipocyte-specific inactivation of the Enpp2 gene encoding ATX." (PMID 29889835, 2018). "Our data suggest Peli3, Creb1, Enpp2, and Centg1 as potential early biomarker candidates for obesity-induced pathophysiological changes in the colon." (PMID 28170448, 2017).
colon carcinoma (7 papers, 2007 to 2024). "Higher methylation of the ENPP2 promoter region is also associated with poor prognosis in prostate and colon cancers." (PMID 39123378, 2024). "pDC development and homeostasis are regulated by the transcription TCF4, which has been reported to be modulated by LPA in colon cancer cells, suggesting that ENPP2 expression from pDCs and the local production of LPA modulates, in an autocrine manner, pDC development and homeostasis." (PMID 34576169, 2021). "Similarly, Enpp2 gene expression in most of colon cancer cell lines is low with an exception of Colo320 cells, which has a neuroendocrine origin." (PMID 31323936, 2019). "Promoter regions of ENPP2 were found hyper-methylated in primary invasive breast carcinomas, while inhibition of histone deacetylases 3 and 7 with trichostatin A also attenuated ENPP2 expression in colon cancer cells, suggesting that ENPP2 expression can be also amenable to epigenetic regulation." (PMID 29951481, 2018).
Insulin resistance (7 papers, 2018 to 2025). Increased resistance towards insulin, that is, diminished effectiveness of insulin in reducing blood glucose levels. "ENPP2 has been reported implication in multiple physiopathological processes, such as dendritic cell migration, adipose tissue expansion, and insulin resistance." (PMID 35958261, 2022).